PIK3CA (phosphatidylinositol-4,5-bisphosphate 3-kinase catalytic subunit alpha)
Diseases named in the same sentence as PIK3CA in open-access papers (continued):
Sharing a sentence is not in itself a finding about the gene and the disease.
lung carcinoma (continued). "To conclude, in this study we report the frequency of EGFR mutations in a cohort of 956 lung cancer patients as well as the frequency of alterations in KRAS, BRAF, MET, PIK3CA and ALK genes in a subset of these patients." (PMID 26208325, 2015). "It is known that activating mutations in the HRAS homolog, KRAS, decrease gefitinib sensitivity in NSCLC, and that activation of the PIK3CA pathway also reduces tyrosine kinase inhibitor sensitivity in EGFR-mutant lung cancers." (PMID 25969993, 2015). "Here we provide a detailed characterization of PIK3CA-mutated NSCLC, to our knowledge in the largest cohort of this genetically defined lung cancer subgroup reported so far." (PMID 25473901, 2015). "In previous studies, miR-1 has been shown not only to target PIK3CA and inhibit the tumorigenic properties of lung cancer cells but also to be useful in predicting lymph node metastasis and postoperative recurrence in patients with NSCLC." (PMID 25874496, 2015). "PIK3CA gene encoding a catalytic subunit of the phosphatidylinositol-3-kinase (PI3K) is mutated and/or amplified in various neoplasia, including lung cancer." (PMID 24533074, 2014). "The PIK3CA pathway consist of the KRAS and EGFR genes which are important targets for many cancers, mutations of PIK3CA have been also identified in lung cancer." (PMID 24369052, 2013). "Treatment of inducible murine lung cancers containing KRAS and PIK3CA mutations with PI3K/mTOR (NVP-BEZ235) and MEK (selumetinib) inhibitors led to an enhanced response." (PMID 23085539, 2012). "Previous studies have shown that a region of chromosome 3q (3q25–27), where PIK3CA (3q26) is located, is frequently amplified in lung cancers, especially squamous-cell carcinomas." (PMID 22928112, 2012). "In contrast, the use of the PI3K inhibitor taselisib did not render significant benefit to patients with the PIK3CA mutation either in a lung cancer study or in an agnostic clinical trial." (PMID 38612902, 2024). "PIK3CA, a catalytic subunit of PI3K kinase, is a highly attractive target as its activating mutations occur at a reasonable frequency across the most common cancer types, particularly breast, colorectal, and lung carcinomas." (PMID 38612902, 2024). "PIK3CA mutations or gains are present in a subset of NSCLC with EGFR mutation and are associated with malignant biological behavior and EGFR-TKIs resistance in lung cancer." (PMID 37553597, 2023). "Knockdown of PIK3CA inhibited colony formation of lung cancer cell lines with PIK3CA mutations or gains but was not effective in PIK3CA wild-type cells." (PMID 37553597, 2023). "The PIK3CA mutation rate was reported to be 1.8% (14/760) in lung cancer without EGFR-TKI treatment." (PMID 35806042, 2022). "PIK3CA is the most studied among PIK3 mutations, with amplification or clustering of somatic mutations occurring in up to 30% of endometrial, breast, ovarian, and colon cancers while PIK3CB is found in thyroid and lung cancers." (PMID 33619913, 2021). "Besides EGFR and PIK3CA, other known mutations were detected in KRAS (n = 4; G12V, G12A, G12D, and Q61H), which have all been reported as driver mutations in lung cancer." (PMID 33407425, 2021). "By contrast, elevated PIK3CA expression has been found in about 32% of lung cancers." (PMID 33572326, 2021). "Our analysis showed differential expression of PIK3CA in NSCLC but there are no reports of PIK3CA gene overexpression being associated with either carcinogenesis or progression of lung cancer." (PMID 33273537, 2020). "PIK3CA mutation is found in ~4% of human LUAD that, although quite rare, still represents a significant patient population due to the high prevalence of lung cancer in our society." (PMID 31452510, 2019). "PIK3CA gene amplifications have been reported in lung cancer." (PMID 31905960, 2019).
lung carcinoma (continued). "Meanwhile activations of other signaling pathways, such as ERBB2 and PIK3CA may mediate resistance of lung cancers to EGFR-targeting therapies." (PMID 28591695, 2017). "It has been hypothesized that a portion of PIK3CA-mutant lung cancers could be dependent on PIK3CA as a driver oncogene, whereas in other cases, the PIK3CA mutation may modulate the effect of another oncogenic process." (PMID 27765909, 2016). "Further studies are warranted to elucidate the clinical and/or biological significance of acquired PIK3CA mutations, KRAS mutations and uncommon EGFR (other than p.T790M) mutations as well as other co-existing resistance mutations in TKI-resistant lung cancers." (PMID 27304188, 2016). "Cell lines with PIK3CA amplification was positively associated with BYL719 sensitivity (P=0.0037) and tumor-bearing mice with PIK3CA amplification responded to BYL719, leading to a response rate of −18% (lung cancer) and −80% (gastric cancer)." (PMID 27016421, 2016). "In addition, the French NCI’s Lung Cancer Mutation Consortium (LCMC) collected 10000 NSCLC for analysis, and the most common co-existing mutations with other drivers in NSCLC is PIK3CA mutation." (PMID 27734950, 2016). "Although many molecular genetic studies have implicated certain genetic mutations in non-small cell lung cancer (NSCLC), including mutations in the EGFR, PIK3CA, BRAF, KRAS, and ALK genes, only a few studies have focused on the genetic events associated with salivary gland-type lung carcinomas." (PMID 26373952, 2015). "The functional effects of mutant or amplified PIK3CA in lung cancer are unclear." (PMID 22363436, 2012). "Known lung cancer genes (EGFR, KRAS G12C, ALK, MET, RET) were found in 33 patients; 11 had genes relevant to both lung and other cancers (ERBB2, BRAF V600, NTRK), and 37 had genes typically linked to other malignancies (NF1, PIK3CA, PALB2, FGFR2B, FBX7, RAD51)." (PMID 40244261, 2025). "Similarly, taselisib exhibited significant tumor regression in PIK3CA-mutant lung cancer." (PMID 39953539, 2025). "Alterations in different components of the PI3K/Akt/mTOR pathway, including somatic mutations of PIK3CA, deletions of PTEN, and increased Akt activity, have been recorded in most NSCLC cases, resulting in this pathway being one of the most frequently deregulated in lung cancer." (PMID 38672636, 2024). "In addition, our investigation identified several targeted therapy drugs that displayed efficacy in their target mutated cell lines, including taselisib and alpelisib (PIK3CA inhibitor) in PIK3CA-mutated CRC, and canertinib and dacomitinib (EGFR inhibitors) in EGFR-mutated lung cancer." (PMID 37863651, 2024). "The rate of positive E20 mutations in the whole blood sample (4.55%) was significantly higher than the other two sample types; however, there were no positive PIK3CA gene mutations detected in exon E20 among patients with different pathologic types or lung cancer stages." (PMID 34217313, 2021). "Additionally, mutations in the KRAS, BRAF, and PIK3CA genes have emerged as an important predictive marker of resistance to epidermal growth factor receptor (EGFR)-targeting monoclonal antibodies or tyrosine kinase inhibitors in colorectal and lung cancers." (PMID 33054840, 2020). "Thus, if the PIK3CA/BRAF prevalence in AEC is validated in a larger study, it would be reasonable to consider trials in which the AEC mutation spectrum is measured before and after treatment of lung cancer subjects bearing cancers that also have the mutation." (PMID 31711466, 2019). "The aim of the current study is to investigate the prevalence of alterations in the eight most frequently altered genes in lung cancer—BRAF, EGFR, KRAS, ALK, ROS1, HER2, PD-L1 and PIK3CA." (PMID 41153394, 2025). "The Solo‐test Driver panel has the potential to identify an additional 18.3%, 16.5%, and 8.7% of RAS+ colorectal, PIK3CA+ breast, and EGFR+ lung cancer patients, respectively, when compared to FDA‐approved PCR tests." (PMID 40056420, 2025).
lung carcinoma (continued). "Targeting specific proteins such as SRC, STAT3, PIK3CA, MAPK1, EGFR, and JAK1 is crucial for impeding the growth of lung cancer." (PMID 38921583, 2024). "For example, the analysis of PIK3CA and EGFR in single viable CTCs from breast and lung cancer patients was analyzed using Sanger sequencing." (PMID 40026568, 2024). "Preclinical studies have indicated that the dual inhibition of the PIK3CA and EGFR pathways demonstrates synergistic cell killing in head, neck and lung cancer models." (PMID 35158773, 2022). "Interestingly, we noted that PIK3CA mutants cooccurred with other genetic alterations that promote enhanced PI3K signaling; for example, mutations in PIK3CA were found concomitantly with mutations in EGFR, KRAS, or ALK in the same tumors of lung cancer patients." (PMID 33827485, 2021). "It was determined that HSP90AA1 hit downstream genes SRC, PIK3CA, and PIK3R1 to modulate lung cancer progression." (PMID 34833921, 2021). "The potential therapeutic targets of bufalin included MDM2, PIK3CA, MAPK14, and MTOR, which can induce cell death through various mechanisms and exert anticancer properties against lung cancer, liver cancer, and other tumors." (PMID 32148531, 2020). "Similarly, human LAD specimens showed colocalization of VAL and Vimentin in the cytoplasm of lung cancer cells, and LAD specimens carrying activating PIK3CA (E545K) mutation presented increased staining intensities of both VAL and Vimentin as compared to those carrying wild-type PIK3CA or AKT." (PMID 33046716, 2020). "Our results show that 2HF induced apoptosis in both histological types of lung cancer and inhibited proliferation and growth through suppression of CDK4, CCNB1, PIK3CA, AKT and RPS6KB1 (P70S6K) signaling." (PMID 30546837, 2018). "Lung cancer is the major cause of cancer-related deaths and many cases of Non Small Cell Lung Cancer (NSCLC), a common type of lung cancer, have frequent genetic/oncogenic activation of EGFR, KRAS, PIK3CA, BRAF, and others that drive tumor growth." (PMID 25466244, 2014). "PIK3CA, XIAP and Rab5a have previously been reported in lung cancer and we have reported the effect of the rest of the mentioned genes for the first time." (PMID 23874428, 2013). "Chromosome copy number abnormalities in lung cancer have been frequently identified using comparative genomic hybridization (CGH) assay, including genomic amplification of PIK3CA which codes the phosphatidylinositol-3-kinase (PI3K) catalytic subunit α." (PMID 21507233, 2011). "Lung cancers showed typical non-small cell lung cancer (NSCLC) driver alterations (KRAS G12D, RET fusions, PIK3CA mutations) and pervasive tumor suppressor loss, with no microsatellite instability (MSI)-high cases." (PMID 41717185, 2026). "Together, these results indicate that PIK3CA is not required for lung cancer cell growth induced by mutant KRAS in vitro but is essential for in vivo progression and growth." (PMID 41892297, 2026).
lung carcinoma (continued). "Together, these results demonstrate that PIK3CA is not required for lung cancer cell growth induced by mutant KRAS in vitro but is critically needed for in vivo progression and growth." (PMID 41676515, 2026). "In the present study, we detected and found that there was no T790M mutation or other mutations including BRAF, PIK3CA, HER2 or c-MET amplifications in these resistant lung cancer cells." (PMID 39744423, 2025). "Notably, PIK3CA genomic gain, as detected by FISH, has been reported in 43% of lung cancers, with a preference for squamous cell carcinoma." (PMID 41394854, 2025). "Another study also found MAPK1 variant, a rare variant in lung cancer, but no other evidence found co-variant with EGFR and PIK3CA." (PMID 38245692, 2024). "Our discovery of PI3Kβ as a target to enhance ALKi sensitivity in ALK‐rearranged lung cancer is unexpected, as we here found combinatorial ALKi/PI3Kβi sensitivity independent of PTEN/PIK3CA mutations or resistance to PI3Kα inhibitors." (PMID 36423211, 2023). "Currently, the evaluation of PIK3CA gene alterations is not recommended in clinical practice since no targeting drugs have been approved to date for lung cancer treatment." (PMID 33807876, 2021). "Studies in lung cancer have not been reported on the co-occurrence of mutations in PTEN and BRAF, but the PIK3CA mutations have been associated with BRAF mutations." (PMID 32034196, 2020). "Further proving that mutations in the RAS-RAF-MAPK pathway often have one hit per tumor, these tumors had no other known mutations in genes often mutated in lung cancer, such as EGFR, KRAS, HER2, or PIK3CA, or BRAF." (PMID 22928112, 2012). "Additionally, in specific cases a relatively high change in Young’s modulus did not correspond to marked expression changes of a given gene — see for example low CAV1 changes observed in MCF10A PIK3CA mutant, or low IGFBP7 changes in intestine and lung carcinoma samples." (PMID 39960760, 2025). "Secondary mutations in the EGFR driver gene are a primary cause of resistance to EGFR-TKIs 2, 3; in addition, other mutations including BRAF, PIK3CA, HER2 or c-MET amplifications, which were independent of EGFR pathway, account for 5-20% in EGFR-TKIs resistant lung cancer." (PMID 39744423, 2025). "However, data from pathology reports are used in routine clinical practice, and common mutations such as EGFR in lung cancer and ESR1 or PIK3CA mutations in breast or colon cancer are not present on the molecular board." (PMID 39457104, 2024). "Notably, KRAS, BRAF, ERBB2, PIK3CA, RET, ROS1, ALK, and NRTK1/2/3 have been proposed as prognostic markers, making substantial contributions to genotype-directed therapies for advanced lung cancer." (PMID 36619227, 2023). "Similarly, apoptosis rate was seen to increase in lung cancer cells exposed to simulated microgravity, as tumor-suppressor genes were upregulated when cells were cultured in a random-positioning machine (RPM), and AKT3 and PIK3CA expression remained unaltered." (PMID 35806469, 2022). "Besides EGFR T790M, other resistance mutations can only be detected by the UltraSEEKTM Lung Panel (in BRAF, ERBB2, KRAS and PIK3CA, as well as EGFR C797S) and could be are useful for treatment decision making for lung cancer patients." (PMID 33081150, 2020).
lung carcinoma (continued). "Almost half (48.4%) of our lung cancer patients had lung squamous cell carcinoma (SCC), which is often perceived to lack molecular targets, however our results suggest that KRAS, PIK3CA, PTPN11 and CDKN2A, in particular, could potentially be actionable targets in lung SCC." (PMID 32087721, 2020). "However, there are targeted therapies for PIK3CA and BRAF driver mutations and mutations at PIK3CA or BRAF hotspots were detected in the AEC of six of the 11 lung cancer subjects and none of the non-cancer subjects." (PMID 31711466, 2019). "Moreover, PIK3CA, the p110alpha catalytic subunit of PI3K, was found to be mutated in approximately 1.3% of Japanese lung cancer patient with EGFR mutations versus 2.1% in patients without EGFR mutations." (PMID 22970367, 2012). "However, this percentage could increase to 71.43%, considering that ESR1 (2.86%), ERBB4 (2.86%), and PIK3CA (8.57%) are not actionable genes in lung cancer." (PMID 39769478, 2024). "In addition to the PIK3CA mutant tumor cells as we tested in this study, we and others also observed that in KRAS mutant and wild-type colon and lung cancer cells, rapamycin could also elicit AKT activation and increase the level of AKT-mediated phosphorylation of PRAS40 on Thr246." (PMID 25961827, 2015). "In total, 57.1% of these patients had no therapy option, since PIK3CA (14.3%), IDH2 (7.1%), and MTOR (7.1%) are not actionable lung cancer genes." (PMID 39769478, 2024).